CIP2A (cellular inhibitor of PP2A)
Diseases named in the same sentence as CIP2A in open-access papers (continued):
Sharing a sentence is not in itself a finding about the gene and the disease.
tumor (continued). "Based on the results of current studies, we examined the expression of CIP2A in CRC cell lines and samples of patients with CRC, and identified the signaling pathways associated with it using a xenograft tumor model and phosphokinase array in CRC cell lines." (PMID 32321509, 2020). "Treating tumour‐bearing mice with EA resulted in significant inhibition of tumour growth with suppression of CIP2A levels and increased autophagy." (PMID 30353639, 2019). "The meta-analysis suggested that CIP2A expression can be a predictive marker of overall survival, disease-specific survival, and time to tumor progression in patients with solid tumors." (PMID 31534561, 2019). "When all of the mice were sacrificed, the tumor specimens were isolated and examined using immunohistochemistry, and the data suggested that the expression levels of CIP2A and EGFR were downregulated in the CuB-treated groups." (PMID 30759826, 2019). "These patterns are no different in LC, with one study finding that 63% of LC tumours express elevated CIP2A protein compared to para-tumour normal tissue." (PMID 31623614, 2019). "In summary, our findings shed light on the tumor-promoting function of Cip2a in TNBC, revealing that this promotion effect is mediated, at least partly, through the up-regulation of miR-301a." (PMID 31762806, 2019). "CIP2A is one of the most common oncoproteins in human malignancy, with approximately 70% of tumours reported to overexpress CIP2A." (PMID 31623614, 2019). "Cancerous inhibitor of protein phosphatase 2A (Cip2a) is an oncogene that is known to inhibit PP2A tumor suppressor activity in human malignancies." (PMID 31762806, 2019). "In turn, CIP-2a promotes tumorigenesis and, in general, tumor progression by inhibiting the activity of protein phosphatase 2A (PP2A)—a prerequisite for the oncogenic transformation of human cells—and by stabilizing c-MYC in different tumors." (PMID 31001477, 2019). "ATF6 protein expression was positively correlated with CIP2A protein expression (P < 0.001) and tumor stages (P = 0.007)." (PMID 30063110, 2018). "High CIP2A expression is seen in over 70% tumor patient specimen and its overexpression can predict response and resistance to chemotherapeutics." (PMID 30044786, 2018). "CIP2A MICI in relation to tumor regression was evaluated in 47 samples from patients having received long‐course (C)RT." (PMID 29441695, 2018). "CIP2A MICI was found to associate with patient age at the time of diagnosis and with the depth of tumor invasion (pT)." (PMID 29441695, 2018). "According to the tumor growth curve, in contrast with FN (+) sh-Control group, tumors in both FN (-) sh-Control group and FN (+) sh-CIP2A group grew at a slower rate, accompanied with significant reductions in tumor size and weight." (PMID 28521777, 2017). "CIP2A depletion reduces both in vitro malignant cellular growth and in vivo xenografted tumor formation." (PMID 28521777, 2017). "It was reported that the tumor suppressor miR-375 represses CIP2A mRNA through multiple miRNA-mRNA interactions, and it is in turn negatively regulated by SNAI1 (Snail)." (PMID 29228564, 2017). "Given the functional context of Akt and CIP2A in cellular regulation, lapatinib-induced interruption of the CIP2A-Akt feedback loop would lead to an extensive impact on its tumor inhibitory effects." (PMID 28938602, 2017). "Our in vivo results also showed that afatinib downregulated CIP2A through Elk-1 in H358 xenograft tumors and inhibited tumor growth." (PMID 25537503, 2015). "Taken together, these results confirmed that afatinib increased PP2A activity to repress p-AKT via CIP2A to inhibit tumor growth in this NSCLC xenografts model." (PMID 25537503, 2015). "Several recent studies have shown that increased CIP2A promotes malignant cell growth, in vivo tumour formation." (PMID 25474139, 2015).
tumor (continued). "Higher CIP2A and Elk-1 expressions were found in the tumor part compared to the non-tumor part, and the expressions of CIP2A and Elk-1 were highly correlated (r=0.733, p<0.001)." (PMID 25537503, 2015). "Immunohistochemical analysis of the tumor specimens demonstrated strong cytoplasmic staining of CIP2A and p-AKT in the vehicles of H358 and H460 cells." (PMID 25537503, 2015). "We examined CIP2A and Elk-1 expressions in paraffin-embedded tumor tissues from patients who underwent surgical resection for NSCLC." (PMID 25537503, 2015). "Together with previously demonstrated essential tumor promoting function for CIP2A in HNSCCs, this data indicate that CIP2A is a driver oncoprotein in HNSCC." (PMID 25474139, 2015). "More importantly, recent studies have also demonstrated that the depletion of CIP2A via siRNAs inhibits xenograft tumor growth." (PMID 24884612, 2014). "Our data demonstrate that high CIP2A expression in patients was associated with poor survival in NPC, and depletion of CIP2A expression inhibited NPC cell proliferation and tumor growth." (PMID 24884612, 2014). "CIP2A in tumor cells from malignant gastric tissues helped to maintain proliferation by preventing cell growth arrest, senescence, or differentiation and CIP2A expression is significantly (P < 0.001) discriminatory between normal and cancerous gastric tissue." (PMID 25015035, 2014). "The secretion of IL-10 by immune and malignant cells, as induced by the E6 protein of human papilloma virus type 16 or 18, contributed to tumor progression by upregulating CIP2A and MYC." (PMID 25015035, 2014). "Targeting CIP2A will be more specific to the tumor cells and also will have limited overall toxicity." (PMID 25015035, 2014). "CIP2A is overexpressed in several tumours, and expression levels are an independent marker for long-term outcome." (PMID 24098375, 2013). "It was shown previously that CIP2A stabilises c-Myc by inhibiting its PP2A-mediated degradation in tumour cells." (PMID 24098375, 2013). "HCC-1937 xenografted and MCF-7 xenografted tumor mice were generated to validate the role of CIP2A in vivo." (PMID 22537901, 2012). "CIP2A has been shown to promote anchorage-independent cell growth and in vivo tumor formation by inhibiting PP2A activity toward c-Myc." (PMID 22537901, 2012). "The level of CIP2A protein expression increased with the stage of disease (12%, 27%, 67%, and 100% for pTa, pT1, pT2, and pT3 tumor, respectively)." (PMID 23342256, 2012). "The frequency of CIP2A expression in high-grade tumor is significantly higher than that in low-grade tumor (P = 0.008)." (PMID 23342256, 2012). "Our data showed that 50/57 (87.7%) tumor samples from TNBC patients demonstrated variable CIP2A expressions." (PMID 22537901, 2012). "In the current study, we performed immunohistochemical (IHC) staining of CIP2A in a tissue array of 57 tumor samples from TNBC patients." (PMID 22537901, 2012). "Next, A549 cells were transfected with NC or CIP2A-specific siRNA, and injected subcutaneously into the right and left flanks of 8 nude mice respectively, and tumor volumes were estimated every two days." (PMID 21655278, 2011). "Among patients with pT2 tumours, however, 5-year survival of CIP2A strongly positive patients was 28.6% (95% CI 0–62.0) compared with 66.7% (95% CI 35.9–97.5) for those with low CIP2A expression (logrank test, P=0.018)." (PMID 21610708, 2011). "We stained tumour tissue microarrays for CIP2A by immunohistochemistry and constructed survival curves according to the Kaplan–Meier method." (PMID 21897396, 2011). "Thereby these results reveal a potential link between deregulated EGFR-MEK1/2-ETS1 pathway signaling and CIP2A-dependent tumor growth." (PMID 21445343, 2011).
tumor (continued). "Immunohistochemistry assay confirmed that CIP2A was dramatically elevated with a higher immunoreactivity score in tumor samples in 26 out of 39 patients (66.7%) tested." (PMID 21655278, 2011). "We found that among the 60 patients, CIP2A was undetectable or very low in paratumor normal tissues, but was dramatically elevated in tumor samples in 38 (63.3%) patients." (PMID 21655278, 2011). "In some types of tumour cells, CIP2A depletion leads to impaired proliferation potential largely due to diminished MYC expression." (PMID 22075943, 2011). "RNA interference (RNAi) may also represent a feasible approach, as CIP2A RNAi treatment inhibited tumor growth in urothelial carcinoma in vitro." (PMID 41155727, 2025). "Notably, KI-AA1524/CIP2A also interacts with several phosphorylated PP2A substrates involved in tumor growth, including c-Myc, polo-like kinase 1 (Plk1), E2F1, Akt, and death-associated protein kinase 1 (DAPK1)." (PMID 41154660, 2025). "Our analysis also depicted three binding sites between miR-577 and CIP2A, suggesting a robust and efficient regulation of the mRNA, ensuring precise control over gene expression by promoting mRNA degradation and inhibiting tumour growth." (PMID 40594400, 2025). "In inhibiting tumor metastasis, the micropeptides CIP2A-BP and miPEP205 play an important role." (PMID 41291707, 2025). "In addition, western blot was performed on tumor mass extracted from a xenograft model using A549 cells expressing shRING1, and similar to the results at the cell level, a tendency for CIP2A and c‐MYC to increase due to RING1 KD was confirmed." (PMID 41362702, 2025). "Notably, this is the first study to link CIP2A with CD31, indicating a novel role in tumor-associated angiogenesis." (PMID 40943297, 2025). "Furthermore, CIP2A contributes to tumor progression by promoting cell proliferation, survival, self-renewal, and resistance to senescence and apoptosis, partly through MEK-mediated activation of ERK signaling." (PMID 41154660, 2025). "Since overexpression of CIP2A can upregulate the drug resistance of tumor cells to chemotherapy, it is plausible that suppressing CIP2A signaling may make tumors that were resistant to some chemotherapies sensitive to this treatment again." (PMID 41155727, 2025). "In 84% of samples with a smoking history, CIP2A was highly expressed in tumor tissues." (PMID 41362702, 2025). "Additionally, immunohistochemical staining of B16 and A375 subcutaneous tumor tissues showed a significant reduction in CIP2A protein levels in the PF‐treated groups." (PMID 39399646, 2024). "Indeed, inhibition of CIP2A by siRNA/shRNA or small compounds suppress cell proliferation in vitro and tumor growth in vivo." (PMID 38321019, 2024). "Expression of CIP2A in various tumor tissues and its clinical significance." (PMID 36911405, 2023). "The SET nuclear proto-oncogene is known to be upregulated in TNBC tumor samples with CIP2A." (PMID 37681908, 2023). "The aim of our present study was to identify whether celastrol exerted its anti-tumor effect by inducing CIP2A rapidly degradation." (PMID 37470692, 2023). "siRNA downregulates CIP2A on tumor cells and potential molecular mechanisms." (PMID 36911405, 2023). "The overexpression of CIP2A/p90 can upregulate the drug resistance of tumor cells to chemotherapy." (PMID 36911405, 2023). "Also, investigating CIP2A-BP upstream regulation would help clarify the comprehensive tumor-suppressive roles of CIP2A-BP." (PMID 35350239, 2022). "Notably, in tumor cells, Chk1 activation is upstream of CIP2A overexpression in response to chronic DNA damage." (PMID 35286657, 2022). "On the other side, it was previously demonstrated that, in addition to its classical role in DNA damage checkpoint regulation, Chk1 activity in tumor cells feeds to cellular phosphoproteome regulation by driving the expression of protein phosphatase 2A inhibitor protein CIP2A." (PMID 35286657, 2022).
tumor (continued). "Interestingly, the review focused on the role of PP2A inhibitors, focusing on CIP2A inhibition, as CIP2A participated in tumor cell growth by stimulating cell-renewal survival, cellular proliferation, evasion of senescence and inhibition of apoptosis." (PMID 36555359, 2022). "In human cancers, CIP2A reduces PP2A’s tumor suppressor action." (PMID 36078884, 2022). "Interestingly, FTY720 has been reported to activate the tumor suppressor PP2A due to its mechanism of action based on CIP2A downregulation and SET blocking, both potent PP2A endogenous inhibitors." (PMID 35329936, 2022). "Moreover, we carried out immunohistochemical analyses in tumor specimens collected at the end of the experiments to evaluate CIP2A/AKT after FTY720 treatment." (PMID 35329936, 2022). "Thus, CIP2A is involved in tumor cell growth by stimulating cell proliferation, survival of cell renewal, evasion of senescence and inhibition of apoptosis." (PMID 36555359, 2022). "In addition, the cancerous inhibitor of protein phosphatase 2A (CIP2A) is a newly recognized oncoprotein that plays a key roles in maintaining cell phenotype, promoting cell proliferation and forming tumours." (PMID 34144694, 2021). "EGFR-TKIs have been found to induce anti-tumour effects via the inhibition of CIP2A." (PMID 31623614, 2019). "Therefore, a promising approach to elucidate the molecular issues involved in the acquisition of an enhanced aggressive phenotype essential for Cip2a-related tumor progression of TNBC is the investigation of dysregulated miRNAs." (PMID 31762806, 2019). "A meta-analysis further indicated that CIP2A expression may be a predictive marker of overall survival, disease-specific survival, and time to tumor progression in patients with solid tumors." (PMID 31534561, 2019). "The level of CIP2A mRNA was significantly correlated with advanced tumor stages and OS." (PMID 30063110, 2018). "CIP2A is an oncogenic cellular inhibitor of PP2A, and overexpression of CIP2A inhibits PP2A, thereby causing various kinase-driven signaling activations, which promote tumor growth and aggressiveness." (PMID 30154367, 2018). "Certain studies have proved CIP2A expression in tumor cells was correlated with poor prognosis." (PMID 30044786, 2018). "MiR-375 may act as a tumor suppressor by targeting CIP2A, and its expression was lower in tumor than in normal rectal tissues, especially among the responders, suggesting downregulation of the miR-375 pathway in these tumors." (PMID 29137264, 2017). "In addition, CIP2A depletion significantly reduced the tumor weight (P<0.05), and CIP2A overexpression significantly increased the tumor weight (P<0.05)." (PMID 29263916, 2017). "The biological function of CIP2A in stimulating tumor progression and drug resistance may relate to AKT signaling pathway." (PMID 26894380, 2016). "Several previous studies have demonstrated overexpression of CIP2A in various tumor types." (PMID 25663244, 2015). "Moreover, the results indicate that high Oct4 and CIP2A expression in HNSCC cells confer HNSCC tumour radioresistancy." (PMID 25474139, 2015). "Neither cytoplasmic nor nuclear CIP2A immunoreactivity was associated with tumor thickness and ulceration in any of the subtypes (data not shown)." (PMID 25663244, 2015). "Consistent with its oncogenic role, overexpression of CIP2A has been found in several tumor types, including ovarian, colon and non–small cell lung carcinoma, as well as in chronic myelogenous leukemia, where it is associated with disease progression and prognostic variables 5,8–15." (PMID 25663244, 2015). "CIP2A depletion resulted in a significant reduction in tumor growth (P < 0.01)." (PMID 24884612, 2014). "Moreover, moderate to high CIP2A expression correlated with high p-Akt expression in these tumor samples." (PMID 25228280, 2014).
tumor (continued). "Thus CIP2A controls oncogenic transcription in tumor cells and the “oncogenic nexus” of CIP2A protein in human malignancies is executed through the stabilization of MYC protein involving PP2A." (PMID 25015035, 2014). "In solid tumors, CIP2A (mRNA or protein) has been shown to be amplified / overexpressed and these expression levels either correlated significantly with tumor stages or served as an independent prognostic marker for disease-free survival (DFS) and overall survival (OS)." (PMID 25015035, 2014). "CIP2A expression is readily detectable in tumor samples from TNBC patients." (PMID 25015035, 2014). "Moreover, our in vivo data showed that both bortezomib and ΔBtz inhibited tumor growth, downregulated CIP2A, P-Akt and induced autophagy in Huh-7 tumors." (PMID 23383345, 2013). "The inhibition of CIP2A by bortezomib leads to tumor cell apoptosis and autophagy." (PMID 24307892, 2013). "It is currently unclear how CIP2A promotes tumour cell invasion and metastasis." (PMID 22075943, 2011). "CIP2A is an auto-antigen that is over-expressed in human neoplasms." (PMID 21655278, 2011). "We showed that CIP2A was over-expressed in 38 (63.3%) tumor specimens assayed by western blotting." (PMID 21655278, 2011). "We test CIP2A expression in 60 patients from Southern China, and report that CIP2A is drastically increased in 63.3% (detected by western blotting) or 67.2% (at mRNA level) of tumor specimens compared to adjacent normal tissues." (PMID 21655278, 2011). "Interestingly, CIP2A-specific siRNA significantly inhibited tumor growth as compared to NC-siRNA (G through I)." (PMID 21655278, 2011). "Our data thus provide a lead compound for CIP2A-targeting anti-tumor therapeutics." (PMID 21655278, 2011). "In multivariate survival analysis, age over 60 years (hazard ratio (HR) 2.18, 95% CI 1.11–4.28, P=0.023), tumour size 21–40 mm (HR 2.48, 95% CI 1.19–5.17, P=0.016), and high CIP2A expression (HR 2.02, 95% CI 1.07–3.82, P=0.030) remained as independent prognostic factors." (PMID 21610708, 2011). "In addition, multivariate analysis indicated that advanced primary tumour stage, distant metastasis and high-CIP2A expression were independent prognostic factors for RCC patients." (PMID 22075943, 2011). "However, in the 60 patient-matched adjacent normal lung tissues, CIP2A was undetectable in 57 (95%) samples, and was weakly expressed in 3 (5%) specimens where its expression was much lower than that in tumor samples of the same patients." (PMID 21655278, 2011). "Furthermore, CIP2A functions as a specific regulatory factor in various tumor types." (PMID 41155583, 2025). "In addition, CIP2A promotes in vivo tumor formation and anchorage-independent cell growth." (PMID 36555359, 2022). "Furthermore, CIP2A is necessary for malignant cellular proliferation and tumor development in vivo." (PMID 36078884, 2022). "Moreover, combined effects of CIP2A with other molecular and environmental factors probably exist and may differ among tumor types." (PMID 31534561, 2019). "Moreover, when MDA-MB-231 cells transfected with either CIP2A-targeted siRNA or scrambled siRNA were injected into the mammary fat pad of athymic mice, CIP2A depletion led to a significant decrease in tumor volume and weight, as measured at the end of the experiment." (PMID 30341686, 2018). "Furthermore, the expression of CIP2A in pre-malignant stage contributed to tumor formation." (PMID 26560124, 2015). "Notably, within five weeks, all mice (3/3) injected with UT-SCC-14 cells (CIP2A/Oct4 double positive) formed large palpable tumours (range 1.8-2.5 cm), whereas only 1/3 mice injected with low CIP2A expressing HNSCC cell line (UT-SCC-50) formed a barely detectable tumour." (PMID 25474139, 2015). "Furthermore, silencing CIP2A suppressed xenograft tumor growth in vivo." (PMID 24884612, 2014). "Importantly, CIP2A expression is readily detectable in tumor samples from TNBC patients." (PMID 22537901, 2012).